NLRP3 (NLR family pyrin domain containing 3)
Diseases named in the same sentence as NLRP3 in open-access papers (continued):
Sharing a sentence is not in itself a finding about the gene and the disease.
bacterial infection (continued). "Inflammation and the activation of the NLRP3 inflammasome are necessary components to fight bacterial infections of the lung." (PMID 39607755, 2024). "Upon bacterial infection, NLRP3 undergoes different types of ubiquitination and thus has different outcomes." (PMID 38789414, 2024). "Bacterial infection was mimicked by the intraglandular injection of lipopolysaccharide (LPS) and nigericin, known to activate the NLRP3 inflammasome." (PMID 36901740, 2023). "We conclude that α toxin by these two different mechanisms triggers the synthesis of pro-IL-1β and NLRP3 components, activation of capase-1, and secretion of mature IL-1β to defend against bacterial infection." (PMID 38089811, 2023). "The NLRP3 inflammasome can be activated by diverse stimuli during bacterial infection, such as potassium efflux." (PMID 35073381, 2022). "As for NLRP-3 inflammasome, research has confirmed that NLRP-3 can be activated in the case of bacterial infection, promoting the synthesis and secretion of downstream IL-1β, IL-18, and other proinflammatory mediators, and then causing extensive tissue damage." (PMID 36157218, 2022). "Regulation of MHC class I gene expression, inflammasome activation in response to bacterial infection through a mechanism involving heterodimerization with NLRP3." (PMID 35204131, 2022). "NLRP3 inflammasome is an important signaling pathway of the innate immune system and is essential for host defense against bacterial infection." (PMID 35123552, 2022). "Bacterial infections have rarely been reported to activate NLRP3 inflammasome via Nek7-NLRP3 interaction, but researchers are gradually paying more attention on it." (PMID 35350616, 2022). "Another nearby gene on chromosome Omy12 was the NLRP3, which has previously been observed functioning to restrict bacterial infection in Japanese flounder." (PMID 35368705, 2022). "Several host factors are also involved in the activation of the NLRP3 inflammasome during bacterial infections." (PMID 35663964, 2022). "Overall, further in-depth molecular mechanisms exploration about the interaction between Nrf2 and the NLRP3 inflammasome would provide mechanistic insights and present a novel target against bacterial infections." (PMID 36389842, 2022). "Activation of the NLRP3 inflammasome affects the development of a wide range of diseases but is also crucial to the host’s defense against bacterial infections and to the elimination of tumors." (PMID 34829842, 2021). "The activation of AIM2 and NLRP3 inflammasomes typically plays positive roles in host defense against bacterial infection." (PMID 34869331, 2021). "NLRC5 was also demonstrated to cooperate with the NLRP3 inflammasome in response to bacterial infection." (PMID 33925158, 2021). "Activation of the NLRP3 inflammasome is regulated by many factors, including bacterial infections and mtROS." (PMID 34895324, 2021). "Although NLRP3 inflammasome activation is critical for driving acute lung inflammation and aids in the clearance of viral and bacterial infections, persistent activation of NLRP3 by irritants leads to the production of IL-1β." (PMID 33419073, 2021). "Increased expression in the Nlrp3 (Cryopyrin) gene suggests that the MCs can have a stronger ability to release pro-inflammatory cytokines such as IL-1β and IL-18 in response to bacterial infection and other insults." (PMID 33479210, 2021). "The activation of the NF-κB pathway promotes the assembly of the NLRP3 inflammasome and the secretion of IL-1β and IL-18 to intracellular bacterial infection." (PMID 33414782, 2020). "NLRP3 is the main inflammasome complex triggered in response to bacterial infections or toxins inducing membrane disturbances, such as mycolactone." (PMID 33338061, 2020). "In many bacterial infections, pathogens activate NLRP3-based inflammation through the secretion of pore-forming toxins by Staphylococcus aureus." (PMID 32148650, 2020).
bacterial infection (continued). "The NLRP3 inflammasome is a multi-protein complex which is activated upon bacterial infections, LMP or cellular damage." (PMID 32668602, 2020). "Recent evidence suggests the involvement of the NLRP3 inflammasome in theinflammatory response induced by caspase-11 in response to bacterial infections thataffect the cytoplasm of host cells such as M. tuberculosis andM." (PMID 32130367, 2020). "NLRP3 inflammasome plays an essential role in host defense against bacterial infection, and its regulation has been extensively studied." (PMID 33120999, 2020). "Cultured human and rat goblet cells were also reported to increase NLRP3 significantly following bacterial infection." (PMID 32019187, 2020). "As NLRP3 inflammasome activation represents critical innate defense mechanism against bacterial infection, we next explored the functional relevance of paclitaxel-mediated augmentation of NLRP3 activation in a mouse model of bacterial infection." (PMID 30761140, 2019). "Activation of the NLRP3 inflammasome is required for host defense against bacterial infections; however, the beneficial antimicrobial role of the NLRP3 inflammasome must be tightly regulated to prevent pathogenic effects induced by excess inflammation." (PMID 31417575, 2019). "Collectively, our results indicated that evodiamine augmented the NLRP3 inflammasome activation through inducing α-tubulin acetylation, thereby conferring intensified innate immunity against bacterial infection." (PMID 30971927, 2019). "During bacterial infection, it has been demonstrated that the activation of caspase-1 by NLRP3 inflammasome inhibits the action of NADPH oxidase." (PMID 31781121, 2019). "Our results suggest that paclitaxel enhanced the innate immune response against bacterial infection by enhancing NLRP3 inflammasome activation through inducing α-tubulin acetylation." (PMID 30761140, 2019). "According to previous studies, various NLR-containing inflammasomes have been reported to be associated with bacterial infection, such as NLRP1, NLRP3, NLRC4, and NLRP6." (PMID 29616195, 2018). "The benefits of this NLRP3-dependent sterile inflammation were evident only when bacterial infection was introduced at the site of lung IR." (PMID 29163464, 2017). "ATP can be released from bacteria or host cells during bacterial infections or sterile tissue damages, thus being an important triggering signal for NLRP3 inflammasome activation." (PMID 29375379, 2017). "As a common in vitro bacterial infection cellular model, J774A.1 cells are often first primed with LPS (first signal), and then stimulated with ATP (second signal) to activate NLRP3 inflammasome." (PMID 27980220, 2017). "In response to bacterial infection, the NLRP3 inflammasome would be assembled for the caspase-1 activation." (PMID 29184853, 2017). "Our findings highlight the indirect antimicrobial effects of berberine against bacterial infection by promoting NLRP3 inflammasome activation and thus augmenting the functions of macrophages." (PMID 27980220, 2017). "As a canonical activator of NLRP3 inflammasome, ATP can be released from both host and bacterial cells in the circumstance of bacterial infection or tissue injury." (PMID 28018360, 2016). "In this respect, the NLRP3 inflammasome plays an important role in IL-1β production in response to bacterial infection." (PMID 28083517, 2016). "In consistence, the ubiquitination of NLRP3 stimulated by ΔYopM bacterial infection was greatly reduced in the cells expressing YopM C68A than YopM WT." (PMID 27929533, 2016). "As a DAMP, ATP release by dead or dying cells can trigger NLRP3 inflammasome activation and proinflammatory release in bacterial infection." (PMID 27779186, 2016). "Although NLRP3 inflammasome activation has a critical role in bacterial infection or other pathological conditions, the signaling pathways regulating this process are still elusive." (PMID 28018360, 2016).
bacterial infection (continued). "In previous studies, mouse macrophages were primed with LPS, which strongly induces TLR4-mediated NF-κB activation, prior to bacterial infection; this would mask NLRP3-mediated NF-κB activation." (PMID 25761061, 2015). "The NLRP3/caspase-1 inflammasome pathway plays an important role in cellular immune defence against bacterial infection; however, its function in human dental pulp tissue and human dental pulp fibroblasts remains poorly understood." (PMID 25684031, 2015). "In conclusion, we showed that NleA negatively modulates host NLRP3 inflammasome activity by interfering with the de-ubiquitin modification of NLRP3 and directly targeting the NLRP3 protein upon bacterial infection." (PMID 26332984, 2015). "Recent studies have found that inflammasomes, especially the NLRP3 inflammasome, plays a pivotal role in fighting bacterial infections." (PMID 23717478, 2013). "In the present study, we demonstrated a protective role for ATP during bacterial infection and this effect was related to NLRP3 inflammasome activation." (PMID 23717478, 2013). "Although the role of ROS in the activation of NLRP3 inflammasome is controversial, several studies have demonstrated that ROS are required for inflammasome activation during bacterial infections." (PMID 22558425, 2012). "The NLRP3 inflammasome is the most extensively studied inflammasome and serves as a primary mediator of inflammatory responses, which plays a crucial role in the host’s defense against bacterial infections and tissue damage." (PMID 41153980, 2025). "NLRP3 is an inflammasome seeding pattern recognition receptor that initiates a pro-inflammatory signalling cascade in response to changes in intracellular homeostasis that are indicative of bacterial infection or tissue damage." (PMID 39838868, 2025). "The role of NLRP3 in bacterial infection has been intensively investigated." (PMID 40034692, 2025). "Therefore, the NF-κB/NLRP3 pathway probably represents a novel therapeutic target for bacterial infections and lung injury." (PMID 40374526, 2025). "Finally, by a mouse model of MDR-KP infection, the data demonstrated that OAY and YHPG ameliorated lung injury and bacterial infections in the lungs, and significantly reduced NF-κB P-p65, NLRP3, and C-GSDMD protein expression in mouse lung tissues." (PMID 40374526, 2025). "This suggests that NLRP3 inflammasome is involved in bacterial diseases in teleosts." (PMID 39211040, 2024). "NLRP3 inflammasome activation is a highly regulated process for controlling the secretion of potent inflammatory cytokines, such as IL-1β and IL-18, which are essential during bacterial infection and the inflammatory response." (PMID 38001788, 2023). "NLRP3 inflammasome activation is a double-edged sword in bacterial infection." (PMID 36798132, 2023). "In addition, Irg-1/itaconate can also inhibit the activation of NLRP3 inflammasomes, thereby combating macrophage inflammation and bacterial infections." (PMID 35145070, 2022). "Several studies have revealed a crucial role of the NLRP3 inflammasome in bacterial infections." (PMID 35663964, 2022). "Several factors have been shown to activate the NLRP3 inflammasome such as phagocytosis of crystalline substances such as silicates or cholesterol but is also triggered by viral and bacterial infection releasing LPS and other TLR ligands as well as DNA and RNA." (PMID 33968032, 2021). "During bacterial infection, many pathogen-associated molecular patterns, such as type III secretion system and lipopolysaccharides, get expressed on the cell wall, which activate inflammasomes, including NLRP3 inflammasome." (PMID 34594329, 2021). "Although additional investigation is needed to clarify the role INF-γ in the current experimental setting, our findings indicated that evodiamine endowed an intensified innate response against bacterial infection likely by enhancing NLRP3 inflammasome activation in mice." (PMID 30971927, 2019).
bacterial infection (continued). "Therefore, the responses of POP2 transgenic primary macrophages to LPS stimulation, Nlrp3 inflammasome activation and bacterial infection were evaluated." (PMID 28580947, 2017). "Thus, we demonstrated that the protective effect of ATP against bacterial infection was, at least partially, dependent on NLRP3 inflammasome activation." (PMID 23717478, 2013). "Accordingly, the inhibition of the NLRP3 and AIM2 inflammasomes by ethanol may contribute to the increased incidence of bacterial infections associated with excessive use of alcohol." (PMID 24244322, 2013). "We next investigated whether the protective effect of ATP against bacterial infection was dependent on the activation of NLRP3 inflammasome." (PMID 23717478, 2013). "Based on the characteristics of ATP, we hypothesized that it would effectively protect mice from bacterial infection, and this effect might be related to NLRP3 inflammasome activation." (PMID 23717478, 2013). "In addition, a pharmacological inhibitor, AC-YVAD-cho, which selectively inhibits the activation of Caspase-1, was used to reveal the role of NLRP3 inflammasome activation in protecting mice from bacterial infection." (PMID 23717478, 2013). "Furthermore, we explored the involvement of Syk kinase activity, which is atypical for bacterial infections, in the NLRP3-dependent events triggered by ESAT-6." (PMID 21740493, 2011). "Indeed, consistent with our in vivo data, studies with WT and Trem2−/− BMDMs have reported an inherent hyperinflammatory phenotype of Trem2−/− BMDM in response to LPS as well as an increased NLRP3 activation in the context of bacterial infection and neuro-inflammation (28, –30)." (PMID 39172787, 2024). "We then assessed whether IpaH4.5 is able to mediate the stabilization of endogenous NLRP3 under physiological conditions by analysis of NLRP3 protein kinetics in response to bacterial infection, and observed that NLRP3 protein levels increased in WT Shigella–infected BMDMs." (PMID 33117724, 2020). "Another study revealed that bacterial infection induces carbon monoxide (CO) production in macrophages, which in turn promotes their bacterial killing and phagocytosis abilities both in vitro and in vivo through increasing the activation of NLRP3 inflammasome and the secretion of active IL-1β." (PMID 27980220, 2017). "With the addition of a bacterial infection to this mix, the role that mitochondria might play in inflammasome activation remains an important subject and may hold the key to allow us to understand the mechanism of NLRP3 activation." (PMID 21731762, 2011). "Ornithine lipids, which function in the pathogenesis of bacterial infection, trigger TLR4 signaling and K+ efflux-dependent NLRP3 inflammasome activation in macrophages." (PMID 40307577, 2025). "However, it remains unclear whether caspase-1 was also activated by caspase-8, as observed in bacterial infections, by active caspases-3/7, which were previously shown to activate NLRP3-dependent inflammation upon TLR signaling, or independent activation of the NLRP3 inflammasome." (PMID 41173854, 2025). "Well-known inflammasome proteins, such as NLRP3 and NLRC4, and Casp4 are intracellular PRRs that induce pyroptosis during intracellular bacterial infections." (PMID 39951384, 2025). "Unlike DHX29 or DDX19A, which act as viral RNA sensors and activators of inflammation through the NF-κB or NLRP3 pathways, DDX5 regulates the m6A modification of TLR2/4 mRNA to suppress inflammatory responses pathway during bacterial infection." (PMID 38182816, 2024). "Mitochondrial oxidative stress-induced release of mtDNA in bacterial infection mediated the secretion of type I IFNs via the cGAS-STING pathway and triggered activation of the NLRP3 inflammasome." (PMID 38195584, 2024).
bacterial infection (continued). "During the inflammatory process of bacterial infection, 13(S)-HOTRE can activate the PPAR-γ receptor to deactivate the NLRP3 inflammatory vesicle complex, resulting in the downregulation of LPS-induced proinflammatory markers." (PMID 38998045, 2024). "Notably, in severe bacterial infection, such as those leading to severe inflammatory responses and disseminated intravascular coagulation, bacteria can trigger coagulation disorders through the caspase-11/NLRP3 pathway, ultimately resulting in fatal complications such as septic shock." (PMID 39011036, 2024). "NLRP3 and ATG5/ATG16L1-mediated autophagy signaling pathway plays an important role in regulating immune response to resist bacterial infections." (PMID 36362066, 2022). "Since pyroptosis is often associated with inflammasome activation, we further tested the role of TREM2 on the activation of NLRP3 and NLRC4 inflammasome, which have been reported as the major inflammasomes induced by pyogenic bacterial infection." (PMID 36068223, 2022). "For example, NLRP3 and NLRC4 are recruited to the same inflammasome complex to elicit inflammatory responses to bacterial infection or flagellin stimulation." (PMID 33446652, 2021). "Inflammatory reactions mediated by the NACHT, LRR, and PYD domain-containing protein 3 (NLRP3) inflammasome contributes to non-small-cell lung cancer (NSCLC) progression, particularly in patients with bacterial infections." (PMID 34457117, 2021). "Primary corneal fibroblast cells expressed NOD1 and NOD2, elevated NLRC4 after bacterial infection, but reduced NLRP1, NLRP3, NOD1, and NOD2 mRNA levels following LPS stimulation." (PMID 32019187, 2020). "During bacterial infection, bacterial ligands or host cell damage is sensed by the inflammasome sensors NLRP1, NLRP3, NLRC4, Pyrin, or AIM2." (PMID 30062052, 2018). "To date, various inflammasome members have been identified, among which NLRP3 and NLRC4 are the most common inflammasomes of the host innate immune system in sensing and reacting to bacterial infection." (PMID 29616195, 2018). "Since NF-κB activation in response to PAMP stimulation and bacterial infection is normal in macrophages from NLRP3−/− or ASC−/− mice, NLRP3 has been considered dispensable for signal 1 in mice." (PMID 25761061, 2015). "NLRP3 agonists may hold therapeutic value for treating early‐stage ALD and those ALD patients with bacterial infections." (PMID 39605303, 2024). "Once NLRP3 inflammasome stimulation triggers endosome leakage, CGRP is released into the cytosol and directly binds to NLRP3, destabilizing the NLRP3-NEK7 complex, thereby inhibiting the NLRP3 inflammasome activation and exacerbating bacterial infection." (PMID 39716330, 2024). "In human myeloid cells, the cGAS-STING pathway was necessary for cytoplasmic DNA-induced NLRP3 activation during viral and bacterial infection; similarly, studies have shown that the STING-NLRP3 axis is critical for the pro-inflammatory response induced by Chlamydia trachomatis and aged macrophages." (PMID 38195584, 2024). "LCN2 is produced during the innate immune response to bacterial infection as a bacteriostatic factor, and we here demonstrated that interactions between LCN2 and NLRP3 could promote neuroinflammation in the early phase of SCI." (PMID 37240031, 2023). "The mechanism of NLRP3 activation and its role in bacterial infection have not been well investigated in epithelial cells." (PMID 38089811, 2023). "Furthermore, it has been reported that the mRNA expression of inflammasome components (NLRP3, ASC, and caspase-1) varies in response to bacterial infections." (PMID 37834004, 2023). "In the bacterial infection-induced NLRP3 inflammasome (non-canonical NLRP3 inflammasome), caspase-11 acts as an intracellular LPS sensor and plays a pivotal role in the activation of caspase-1." (PMID 35345462, 2022).